HIF1A (hypoxia inducible factor 1 subunit alpha)
Diseases named in the same sentence as HIF1A in open-access papers (continued):
Sharing a sentence is not in itself a finding about the gene and the disease.
tumor (continued). "Peripheral and central hypoxia could be clearly distinguished at days 14 or 21; this was further confirmed by the expression of HIF-1α and CAIX, which are several frequently-used hypoxia-associated markers that indicate different biological mechanisms of tumor hypoxia." (PMID 31106146, 2019). "Furthermore, nuclear HIF-1α in RCC tumor tissues predicted a poor MFS and more metastasis." (PMID 30177838, 2019). "Thus, improving tumor oxygenation could inhibit HIF-1α secretion, and then reduce the downstream VEGF protein level." (PMID 31695774, 2019). "Furthermore, HIF1α-induced PFKFB4 mRNA expression correlates with glioma tumor grade." (PMID 30234009, 2018). "Significant changes in VEGF concentrations in patients were observed during a treatment cycle of sunitinib, which is in line with a previous report, in which the authors speculate that this effect is secondary to increased activity of HIF-1α, leading to treatment-related increases in tumor hypoxia." (PMID 29532289, 2018). "Tumours adapt to chronic hypoxia inducing changes in gene expression through the activation of pro-survival and metastatic genes such as nuclear factor kappa beta (NF-κB), Hypoxia-inducible factor-1-alpha (HIF-1-α), PIM-1 oncogene (PIM-1) and endothelin-1 (EDN 1)." (PMID 30595759, 2018). "In cases where tumor growth exceeds the ability of the host’s vascular system to supply the tumor microenvironment with sufficient oxygen, hypoxic regions are established that induce HIF-1α activation and instruct cancer cells to utilize glucose causing an increase in lactate release." (PMID 30619850, 2018). "The results suggest that HIF-1α may promote tumor dissemination to bone." (PMID 30423905, 2018). "While the exact mechanism by which excess succinate leads to transformation and why it is only associated with these rare tumor types are currently unknown, suspected culprits include excess ROS, HIF-1α stabilization, aberrant genome methylation, and tumor-promoting inflammatory changes." (PMID 29706933, 2018). "We were able to show that low EGFR mRNA expression and low HIF-1α mRNA expression are associated with a poorer prognosis for STS patients, but in particular, the combination of both markers appears to be a helpful tool to assess the risk of tumor-related death of STS patients." (PMID 30513863, 2018). "Therefore, we hypothesized that in tumors with increased necrosis or HIF-1α staining, nimotuzumab could mediate tumor-protective effects resulting in decreased survival of patients." (PMID 30129426, 2018). "Notably, HIF1A activity appears to be suppressed in POLE-category tumours." (PMID 29880869, 2018). "Moreover, targeting HIF-1α may be a potential target for inhibiting tumor tumorigenesis and EMT by decreasing cancer cells wound healing and anchorage-independent colony growth." (PMID 29587825, 2018). "Furthermore, our results indicate that elaiophylin could inhibit tumor angiogenesis by downregulating both the VEGFR2 signaling pathway in endothelial cells and the HIF-1α levels in tumor cells, thereby resulting in the reduction of tumor growth." (PMID 29498688, 2018). "Finally, melatonin also suppresses tumor angiogenesis by inhibiting not only HIF-1α accumulation through suppression of the melatonin nuclear receptor RZR/RORγ and the SUMO-specific protease 1 (SENP1) signaling pathway but also VEGF production in human gastric cancer cells under hypoxia." (PMID 29844288, 2018). "However, genetic editing may carry an increased risk of malignant transformation of MSCs due to sustained dysregulation of HIF-1α expression, particularly since HIF-1α has been implicated in tumor development and invasiveness." (PMID 29780805, 2018). "It has been wondered whether the increased expression of HIF1A in cancer cells is a consequence of the necessity for adaptation to the hypoxic tumor microenvironment or it is an intrinsic initiating event of the tumor development." (PMID 29937761, 2018).
tumor (continued). "Although it was suggested that temporal increases in HIF-1α may lead to tumor reoxygenation and may therefore be beneficial in particular cases, the role of HIF-1 in therapy resistance is irrefutable and its upregulation via heating may most likely be detrimental." (PMID 30420794, 2018). "Notably, candesartan, an ARB, significantly decreased HIF-1α protein levels of hypoxic tumor cells." (PMID 28205588, 2017). "HIF-1α upregulates the levels of cathepsin D (CTSD), urokinase-type plasminogen-activator receptor (uPAR), and matrix metalloproteinase-2 (MMP2) enzymes, implicated in the basement membrane disruption leading intravasation and dissemination of circulating tumor cells (CTCs) in the organism." (PMID 28781970, 2017). "It is important to note that in vivo, HIF-1α is expressed in chronically hypoxic tumor regions, which could be partly due to genetic events or oxygen-independent stabilization by several stimuli present in the tumor microenvironment." (PMID 29317983, 2017). "Indeed, GlcNAcylation has beenlinked to HIF1α protein expression by one study in tumour cells." (PMID 28555668, 2017). "However, the network regulating tumor biological behaviors is exceedingly complicated, andRPS6KB1 could also work via other signaling pathways, such as miR-128/ HIF-1α/PKM2." (PMID 28792981, 2017). "Therefore, we sought to demonstrate whether in hypoxic tumor cells Ang II is involved in the accumulation of HIF-1α protein, a key regulator of the hypoxic response." (PMID 28205588, 2017). "Additionally, hypoxia induced by medical or surgical treatment induces the accumulation of HIF-1α inside tumor cells and its subsequent migration into the nuclei, where it promotes the expression of angiogenesis-related genes and increases oxygen supply to the tumor." (PMID 28053598, 2017). "Furthermore, HIF1α supports energy supply to hypoxic tumor cells driving an anaerobic glycolysis by upregulating monocarboxylate transporter 4 (MCT4) that exports the lactate out of the cells and influencing carbonic anhydrase IX (CAIX) to prevent the intracellular acidification." (PMID 28447025, 2017). "Additionally, we did not directly measure hypoxia or perfusion in these experiments and can only speculate as to the role that differences in these physiologic parameters would have had on tumor growth and the Hif1-α signaling pathway." (PMID 29254140, 2017). "Tumor suppressive miRNAs mediate the degradation or post-transcriptional inhibition of transcripts encoding oncogenes and can target ZEB1/2, HMGB2, Bcl2 and HIF-1α, which contribute to the increased proliferation, invasion, and EMT and reduce the apoptosis of cancer cells." (PMID 28085956, 2017). "As a redox signaling protein, Ref-1/APE1 enhances the transcriptional activity of STAT3, HIF-1α, nuclear factor kappa B, and other transcription factors to promote growth, migration, and survival in tumor cells as well as inflammation and angiogenesis in the tumor microenvironment." (PMID 28825044, 2017). "Most importantly, our results showed that this interaction was dramatically disrupted by transfection of miR-1 mimics, which may be largely attributed to reduction of HIF-1α expression by miR-1 mimics, leading to decrease phosphorylation of Smad3 and inhibit tumor glycolysis." (PMID 28471448, 2017). "Thus, NRF2 could function as a positive regulator of HIF-1α activity in tumors and is coordinately involved in tumor progression." (PMID 29050246, 2017). "Therefore, in tumour-infiltrating NK cells, HIF-2α may compensate for the loss of HIF-1α during long-term exposure to hypoxia in the microenvironment." (PMID 29150606, 2017). "We surmised that targeted inhibition of CAs by AZ could interfere with the hypoxia induced HIF1-α mediated regulation of tumor cell pH homeostasis with likely consequences to other HIF1-α regulated processes required for tumor cell growth, progression, and survival." (PMID 28235409, 2017).
tumor (continued). "Thus, HIF-1α, along with its signaling pathway, is vital for tumor invasion and metastasis." (PMID 28076840, 2017). "At the same time, excessive pruning of tumor vasculature over time could aggravate hypoxia in the tumor microenviroment, resulting in high hypoxia-inducible factor-1α (HIF)-1α levels, which enhances immune checkpoint molecules expression such as PD-L1 in MDSCs and macrophages." (PMID 28420805, 2017). "Therefore, HPßCD-HET0016 may be acting as an inhibitor of inflammation and angiogenesis growth responses in GBM tumor cells through regulating HIF-1α and VEGF." (PMID 28139732, 2017). "Interestingly, 3D2-3, but not 3D1 stage MCTS or cells cultured in 2D, displayed expression of hypoxia-inducible factor 1α (HIF-1α) protein, typically detectable in hypoxic areas, similar to tumor xenografts generated in vivo upon s.c. injection of the same cells in immunodeficient animals." (PMID 27965457, 2017). "Furthermore, targeted deletion of HIF-1α in myeloid cells resulted in reduced tumor growth." (PMID 28348554, 2017). "PKM2 is upregulated in tumours and is essential for aerobic glycolysis, it exists as an enzymatically inactive monomer/dimer in the cytosol, which can translocate to the nucleus to activate pro-glycolytic and HIF-1α dependent genes by forming a PKM2-HIF-1α complex." (PMID 28225071, 2017). "We found that the more slowly growing tumours from HIF-1α KO mice had markedly increased levels of hypoxia determined by Glut1 staining, which also occurred in areas with high vessel density along with increased tumour cell death as assessed by caspase 3 staining." (PMID 29150606, 2017). "Moreover, hypoxia may protect tumor cells from antitumor immunity and can promote HIF1α-dependent transcriptional upregulation of PD-L1 on cancer cells and myeloid-derived suppressor cells (MDSCs) that may inhibit PD-1-expressing T cells." (PMID 27510264, 2016). "The results of this study suggested that the plasma level of HIF-1α maybe provide a possible direction for further research and test, such as research on new therapeutic target of drugs based on HIF and the determination of drug-sensitive tumor types for HIF-1α inhibitors." (PMID 26853843, 2016). "Even though HIF-1α is exclusively localized in the nucleus of most cancer cells, it will be interesting to examine whether the ability of DAPK to promote HIF-1α degradation in the cytoplasm also contributes to the tumour suppressing function of DAPK in selective cancer types." (PMID 27312851, 2016). "In order to investigate whether there was an association between mPGES-1, Dicer expression and VEGF/angiogenesis in these samples we assessed expression levels of mPGES-1 with Dicer and angiogenic markers (CD31, VEGF and HIF-1α) in human specimens with different tumor grade/staging." (PMID 27322147, 2016). "In addition, TRAF6 is reported to increase HIF-1α expression and promote tumor angiogenesis." (PMID 27791197, 2016). "Since the expression of HIF1α or HIF2α has been detected at higher level in tumor tissues compared to the tumor surrounding tissue, we can hypothesize that the high expression of HIF2α in peritumoral tissue might be seen as a further sign of an initial transformation." (PMID 27705944, 2016). "Therefore, HBx may facilitate the adaptation of tumor cells to low oxygen conditions through HIF-1α upregulation, allowing tumor cells to survive in this harsh microenvironment." (PMID 27658781, 2016). "Similarly, since HIF-1α might regulate the expression of CXCR4, we examined the expression of HIF-1α in implanted tumor tissue." (PMID 27175473, 2016). "Therefore HIF1α expression and stabilization may actually inhibit tumor B cell infiltration and thus may be a protective mechanism in response to tissue hypoxia." (PMID 27437104, 2016). "Interestingly, the risk of tumor-related death for the patients’ groups with the worst prognosis was comparable independent of HIF-1α alone (RR = 4.53)." (PMID 27044404, 2016).
tumor (continued). "Another caveat concerns the observed magnitude of mPGES-1 effect in tumor xenografts on VEGF/HIF-1α up-regulation and tumor growth, suggesting that other miRNAs than miR-15a and −186, downstream to Dicer inhibition, and other target than VEGF, might be involved." (PMID 27322147, 2016). "Finally, myeloid-specific HIF-1α is an important mediator of the formation of the VM network in both matrigel and tumors since its ablation leads to a decrease in network formation, plug perfusion and tumor growth." (PMID 27834402, 2016). "Therefore the identification of key cofactors of HIF-1α that could activate complex tumor and angiogenic responses might help in the development of more efficacious antitumoral treatment." (PMID 26909598, 2016). "HIF1α regulates tumor behavior, promoting proliferation, apoptosis and migration; thus, inhibition of the HIF1α pathway may be a promising strategy for inhibiting tumor progression." (PMID 27556184, 2016). "In addition, HIF-1α is involved in tumor lymphoangiogenesis." (PMID 27044404, 2016). "Therefore, the role of HIF1α in tumor progression has been controversial." (PMID 26841847, 2016). "Moreover, after dissection of the various mechanisms involved, our results showed a strong impact of VDAC1 on tumor development, through alterations in the inflammatory response as a result of an abnormal vasculature due to ROS production and HIF-1α stabilization." (PMID 27625993, 2016). "Therefore, HIF1α plays a suppressive role when the microenvironment of tumor is oxygen sufficient." (PMID 26841847, 2016). "Moreover, deletion of Hif1a reduces tumor-initiating cell (TIC) frequency and activity in vivo." (PMID 27001172, 2016). "IDH1 could also influence tumour phenotype by regulating HIF1α (refs 6,7,23,24)." (PMID 27820599, 2016). "In addition, we have found that buflain could downregulated HIF-1α and increased necrosis in tumor tissues, we hypothesize that microvessels may be inhibited by bufalin." (PMID 26958938, 2016). "However, it is important to identity more unknown targets and to reveal the link between HIF-1α activation and other oncogene or tumor suppressors." (PMID 26057751, 2015). "One may be a mutation or silencing of the von Hippel-Lindau (VHL) gene which is present in over 50 % of cases and is thought to lead in the accumulation of hypoxic-inducible factor 1-alpha (HIF1A), which then creates angiogenesis leading to further tumor growth and potential disease spread." (PMID 26510665, 2015). "However, whether LMWF attenuates hypoxia-induced tumor angiogenesis and the involvement of HIF-1α remains unknown." (PMID 26193287, 2015). "With the regulation of hypoxia-inducible factor 1α (HIF-1α), expression of the angiogenic gene is activated to elevate the level of vascular endothelial growth factor, and endothelial progenitor cells are increased, subsequently promoting tumor neovascularization." (PMID 26036625, 2015). "Univariate analysis revealed that negative staining of ER (P = 0.007, odds ratio (OR) = 3.49), nNHERF1 (P = 0.039, OR = 4.41), HIF-1α (P = 0.032, OR = 2.78) and BRCA1 (P = 0.035, OR = 2.56) and positive cBRIT1 (P = 0.02, OR = 3.11) expression were significantly associated with large tumor size." (PMID 26312763, 2015). "Therefore, it is difficult to detect the chemiluminescence of the Luc expression due to the significantly reduced numbers of hypoxic cells in the tumor tissues versus in vitro experiments, resulting in smaller levels of enhancement of HIF-1α in the living body." (PMID 26034980, 2015). "Activation of Akt may increase cell viability after inhibition of mTORC1, or could potentially the production of increase vascular endothelial growth factor (VEGF) because PI3K/Akt signaling induces tumor angiogenesis by regulating VEGF via both HIF1α-dependent and -independent mechanisms." (PMID 25784113, 2015).
tumor (continued). "In this study, we aimed to compare the efficacies of PX-478 (a specific HIF-1α inhibitor) and chemotherapy drug Gem, as a single agent or in combination, in inducing anti-tumor immune response and immunogenic elimination of PDAC tumor in immune-competent and immune-deficient PDAC-engrafted mice." (PMID 25544770, 2015). "The expression of the transcription factor, hypoxia-inducible factor-1α (HIF-1α), is mainly induced by hypoxia and is known for its ability to induce proliferative and transformative changes in cells; its expression has been shown to correlate with tumor invasion and metastasis." (PMID 25777304, 2015). "Furthermore, to support our hypothesis, we measured HIF-1α expression in tumor tissues and autophagy markers in tumor tissues obtained from NSCLC patients." (PMID 26553068, 2015). "As the primary cellular and systemic response to hypoxic stress, tumor cells in these regions induce the production of hypoxia-inducible factors (HIFs), master transcription regulators that consist of two subunits, the α subunit (HIF-1α, HIF-2α and HIF-3α) and the β subunit (HIF-1β) (Arnt)." (PMID 26034980, 2015). "Thus, further studies are needed to address the functional link between RBM38 and HIF1α under the hypoxic tumor microenvironment, which may explain how tumors thrive under a hypoxic condition." (PMID 25622105, 2015). "Concomitantly, upon ERK inactivation, the decreased level of HIF-1α in the miR-622-overexpressing A549 cells was restored upon transfection with either of two shFOXO3a constructs, which also resulted in enhanced tumor cell invasiveness compared with control oligonucleotide-transfected cells." (PMID 26528854, 2015). "PPZ could suppress tumor growth acting as an HIF-1α protein inhibitor." (PMID 29147412, 2015). "Hence, more studies are needed to elucidate the biological functions of both GLUTs and regulatory molecule HIF-1α in the carcinogenic process, and their possible clinical significance as parameters of tumor invasiveness and prognostic factors in this type of neoplasm." (PMID 25412955, 2015). "Although prior intermittent induction of HIF1α(PP) had hardly any effect on U-87 MG cell proliferation in culture and in vivo, it is noticeable that the bioluminescent signals from the derived tumors permeated broadly beyond the frontal lobes of the brain, indicative of spreading of tumor cells." (PMID 25893706, 2015). "Moreover NTG can reduce HIF-1α levels in hypoxic tumour tissues and this may have anti-angiogenic, pro-apoptotic and anti-efflux effects." (PMID 26435741, 2015). "Furthermore, HIF-1α staining intensity was positively correlated with GLI1 expression, an important component of SHH pathway, in NB tumor samples, which suggests HIF-1α as well as SHH signaling may play an important role in NB initiation or progression." (PMID 25811359, 2015). "HIF-1α is known to trigger adaptive responses during low oxygen conditions, thereby transcriptionally activating many genes involved in many aspects of cancer metabolism including angiogenesis, invasion, metastasis, glycolysis, tumor survival, and proliferation." (PMID 26469226, 2015). "Furthermore, the mitochondrial tumour suppressor Sirtuin 3 promotes destabilization of HIF1α." (PMID 25974097, 2015). "Thus, the article discusses a current knowledge of HIF-1α/2α signaling pathways in the promotion of undifferentiated tumor phenotype in general, including some experimental findings specific for pseudo-hypoxic ccRCC, mostly dependent from HIF-2α oncogenic functions." (PMID 26210994, 2015). "Moreover, whether HIF-1α acts as a driver in the development of endocrine resistance, or simply as one of the markers indicating hypoxia within the tumor remains to be clarified." (PMID 25929338, 2015).